ERGIC3 (ERGIC and golgi 3)
Description:
Possible role in transport between endoplasmic reticulum and Golgi. Positively regulates trafficking of the secretory proteins SERPINA1/alpha1-antitrypsin and HP/haptoglobin.
Synonyms: C20orf47; ERV46; SDBCAG84; CGI-54; PRO0989; NY-BR-84; C2orf47; dJ477O4.2
Tractability: Antibody: UniProt predicts a signal peptide or a membrane-spanning region. PROTAC: ubiquitination databases record sites on it; its protein half-life has been measured.
Gene: Protein-coding gene on chromosome 20 (35,542,024 to 35,557,634, forward strand). Ensembl gene ENSG00000125991.
Subcellular location: Endoplasmic reticulum-Golgi intermediate compartment membrane; Golgi apparatus, cis-Golgi network membrane; Endoplasmic reticulum membrane
Gene Ontology:
Molecular function: protein binding
Biological process: endoplasmic reticulum to Golgi vesicle-mediated transport; retrograde vesicle-mediated transport, Golgi to endoplasmic reticulum
Cellular component: endoplasmic reticulum membrane; endoplasmic reticulum-Golgi intermediate compartment; endoplasmic reticulum-Golgi intermediate compartment membrane; membrane; retrograde transporter complex, Golgi to ER; transporter complex; COPII-coated ER to Golgi transport vesicle; endoplasmic reticulum; Golgi membrane; Golgi apparatus
Genetic constraint (gnomAD): Loss-of-function variants: 33 observed, 56.47 expected, observed/expected ratio (o/e) 0.58, 90% interval 0.44 to 0.78. The upper end of that interval is the gene's LOEUF score, 0.78, which puts it in group 3 of 6, group 1 being the genes least tolerant of losing a copy. Missense variants: 399 observed, 505.36 expected, observed/expected ratio (o/e) 0.79, 90% interval 0.73 to 0.86. Synonymous variants: 186 observed, 197.33 expected, observed/expected ratio (o/e) 0.94, 90% interval 0.84 to 1.06.
Homologues: Orthologues: chimpanzee ERGIC3 (100% identical), macaque ERGIC3 (100% identical), guinea pig ERGIC3 (99% identical), rat Ergic3 (99% identical), mouse Ergic3 (98% identical), dog ERGIC3 (98% identical), pig ERGIC3 (98% identical), rabbit ERGIC3 (90% identical), zebrafish ergic3 (87% identical), tropical clawed frog ergic3 (86% identical), Drosophila melanogaster CG7011 (45% identical), Caenorhabditis elegans ergi-3 (43% identical). Paralogues in human: ERGIC2 (31% identical), ERGIC1 (26% identical).
Diseases named in the same sentence as ERGIC3 in open-access papers:
ERGIC3 is named in the same sentence as 13 diseases in open-access papers, as found by Europe PMC text mining. Sharing a sentence is not in itself a finding about the gene and the disease. The quoted sentences say what the papers report.
hepatocellular carcinoma (4 papers, 2014 to 2022). A malignant tumor that arises from hepatocytes. "For ERGIC3 gene, its overexpression was associated with epithelial to mesenchymal transition in hepatocellular carcinoma cells where activating miR-490-3p targets this gene." (PMID 24475022, 2014). "In addition to lung cancer, ERGIC3 is also associated with hepatocellular carcinomas, and its expression is enhanced in colorectal tumors." (PMID 27588471, 2016). "Reports have demonstrated that ERGIC3 is an tumor-related gene and promotes the malignant biological behavior of tumors including hepatocellular carcinoma derived from liver tissue, where metabolism is active and needs a large number of transporter proteins." (PMID 35602902, 2022). "Previous studies found that miR-490-3p regulates the growth and EMT of hepatocellular carcinoma cells by targeting ERGIC3." (PMID 35602902, 2022). "ERGIC3 correlates with cell proliferation, migration and epithelial to mesenchymal transition in hepatocellular carcinomas (HCC)." (PMID 27588471, 2016). "Thus, transcriptome sequencing and bioinformation was used to investigate the molecular mechanism of ERGIC3 facilitating the growth of hepatoma." (PMID 35602902, 2022). "Accordingly, ERGIC3 may regulate the hepatoma growth by the transport of growth factors such as VEGF receptor, cytokine receptor and collagen." (PMID 35602902, 2022). "However, miR-490-3p modulates cell growth and EMT in hepatocellular carcinoma cells by targeting ERGIC3." (PMID 26843615, 2016). "Therefore, we speculated that ERGIC3 knockdown may inhibit the proliferation and metastasis of human hepatocellular carcinoma SMMC-7721 cells by affecting the miRNA pathway." (PMID 35602902, 2022).
lung adenocarcinoma (2 papers, 2013 to 2016). A carcinoma that arises from the lung and is characterized by the presence of malignant glandular epithelial cells. "ERGIC3 was over-expressed in human lung adenocarcinoma (Grade I, II and III) compared to normal lung tissues." (PMID 27588471, 2016).
lung carcinoma (2 papers, 2013 to 2016). "Over-expression of ERGIC3 in lung cancer tissue led us to study the effect of ERGIC3 knockdown for lung cancer therapy." (PMID 27588471, 2016). "In this study, we show that delivery of a small hairpin RNA targeting ERGIC3 (shERGIC3) suppresses lung cancer through ER stress-induced autophagic cell death in both in vitro and in vivo experiments." (PMID 27588471, 2016). "Knockdown of ERGIC3 led to ER stress-induced autophagic cell death and suppression of proliferation in the A549 human lung cancer cell-line." (PMID 27588471, 2016). "In our study, ERGIC3 was found positive in 89% specimens of lung cancer by immunohistochemical staining." (PMID 23374247, 2013). "The ERGIC3 protein was also over-expressed in lung cancer tissues and cultured cells, and expression of ERGIC3 was correlated with the differentiated degree and histological type of lung cancer." (PMID 23374247, 2013). "We further investigated pathophysiological functions of the altered expression of ERGIC3 in lung cancer cells." (PMID 23374247, 2013). "Through the systematic and serial screening, we found that the ERGIC3 mRNA and protein were highly over-expressed in lung cancer cells." (PMID 23374247, 2013). "In the first stage of the screening for 16 genes, two novel lung cancer-related genes (ERGIC3 and LPCAT1) were found." (PMID 23374247, 2013). "Our data suggest that suppression of ERGIC3 could provide a framework for the development of effective lung cancer therapies." (PMID 27588471, 2016). "Moreover, the relation between increased cancer cell growth and epithelial-mesenchymal transition with ERGIC3 led us to investigate the therapeutic effect of ERGIC3 downregulation in lung cancer." (PMID 27588471, 2016). "Therefore, we confirmed that suppression of ERGIC3 decreased Akt1 activation and lung cancer cell proliferation." (PMID 27588471, 2016). "ERGIC3 was strongly expressed in lung cancers, and that ERGIC3 could promote the cellular proliferation and migration." (PMID 23374247, 2013). "Similarly, expression of ERGIC3 protein was increased in all three lung cancer cell lines by comparison with the BEAS-2B." (PMID 23374247, 2013). "The two libraries of differentially expressed genes may provide the basis for new insights or clues for finding novel lung cancer-related genes; several genes were newly found in lung cancer with ERGIC3 seeming a novel lung cancer-related gene." (PMID 23374247, 2013). "ERGIC3 was mainly located at the Golgi apparatus and ER in the lung cancer cell lines." (PMID 23374247, 2013). "Importantly, this means that for the first time, over-expression of ERGIC3 and LPCAT1 have been linked to lung cancer." (PMID 23374247, 2013). "This prompted us to assess whether knockdown of ERGIC3 may decrease lung cancer growth." (PMID 27588471, 2016). "ERGIC3 may play an active role in the development and progression of lung cancer." (PMID 23374247, 2013). "ERGIC3 is located in endoplasmic reticulum and Golgi apparatus of NRK cells, however, the function of ERGIC3 is unclear in lung cancer." (PMID 23374247, 2013). "Through q-RT-PCR analysis, we found six genes (DDR1, HSP90B1, SDC1, RPSA, ERGIC3, and LPCAT1) significantly up-regulated and two genes (GPX3 and TIMP3) significantly down-regulated in the lung cancer tissues." (PMID 23374247, 2013). "Over-expression of two genes (ERGIC3 and LPCAT1) had not been previously linked to lung cancer." (PMID 23374247, 2013).
colorectal cancer (1 paper, 2013). A primary or metastatic malignant neoplasm that affects the colon or rectum. "LPCAT1 may contribute to total choline metabolite accumulation via phosphatidylcholine remodeling, thereby altering the colorectal cancer lipid profile, a characteristic of malignancy, but this was investigated in a separate work as the current study focuses on ERGIC3." (PMID 23374247, 2013).
liver cancer (1 paper, 2022). An epithelial or non-epithelial malignant neoplasm that arises from the liver. "In order to further reveal the molecular mechanism of ERGIC3 promoting the growth of liver cancer cells, ERGIC3 was knocked down in SMMC-7721 cells by RNAi technology." (PMID 35602902, 2022). "In addition, the high expression of ERGIC3 was positively correlated with the infiltration of B cells, macrophage, myeloid dendritic cells, CD4+ T and other immune cells, suggesting that ERGIC3 may affect the prognosis of liver cancer patients by raising the abundance of infiltrating immune cells." (PMID 35602902, 2022).
cancer (5 papers, 2016 to 2024). A tumor composed of atypical neoplastic, often pleomorphic cells that invade other tissues. "Like importins, ERGIC3 is also strongly implicated in several cancers, but its molecular function has not been thoroughly investigated." (PMID 33054972, 2020). "We hypothesized that abnormal expression of ERGIC3 resulted in transport disorder of factors associated with cell proliferation as well as other active biomolecules, which could affect the growth of cancer cells." (PMID 35602902, 2022). "In conclusion, our data showed that knockdown of ERGIC3 triggers ER stress-induced autophagic cancer cell death and the suppression of Akt1 activation." (PMID 27588471, 2016). "However, the molecular mechanism of ERGIC3 promoting the growth of cancer cells still needs to be further explored." (PMID 35602902, 2022). "ERGIC3 is over-expressed in cancer, and also correlates with oncogenic lung diseases." (PMID 27588471, 2016). "In our study, we focused on the anti-cancer effect of the ERGIC3 downregulation." (PMID 27588471, 2016). "Therefore, ERGIC3 could be a novel target and marker for various cancers and cancer gene therapy." (PMID 27588471, 2016). "In turn, overexpression of miR-490-3p, by stimulating ERGIC3 and inhibiting PCBP1, promotes the proliferation and migration of cancer cells and disturbs the body’s natural immune response, taking part in the development of many cancers, including MM." (PMID 38473390, 2024). "Furthermore, we focused on the seven lncRNAs (PFKL, TPD52, ERGIC3, CFL1, CARS, IARS, and H19), which were related to cancer development." (PMID 32485786, 2020).
tumor (4 papers, 2013 to 2025). "Some binding partner proteins of ERGIC3 are also localized to ER and Golgi apparatus Moreover, knockdown of ERGIC3 suppressed proliferation and tumor growth." (PMID 27588471, 2016). "Moreover, there was a weak positive correlation between the expression of ERGIC3 and tumor purity (r = 0.172, P < 0.05)." (PMID 35602902, 2022). "Expression of ERGIC3 was increased in 67% (10/15) of the tumor cases." (PMID 23374247, 2013). "ERGIC3 was diffusely distributed in the cytoplasm of tumor cells but not expressed in normal bronchial epithelial cells and alveolar cells." (PMID 23374247, 2013). "It indicated that the related genes regulated by ERGIC3 played an important role in PI3K-Akt, NOD-like, Jak-STAT, NF-kappa B and other protein kinase-coupled receptors mediate signal transduction pathways, tumor nonspecific immune response, collagen-integrin receptor-actin axis, and miRNA pathways." (PMID 35602902, 2022).
ERGIC3 also shares sentences with these, for which no sentence is quoted: breast carcinoma (1 paper); colorectal tumors (1); diabetes (1); endometrial carcinoma (1); lung adenoma (1); type 2 diabetes (1).